TNF (tumor necrosis factor)
Diseases named in the same sentence as TNF in open-access papers (continued):
Sharing a sentence is not in itself a finding about the gene and the disease.
vitamin A deficiency (4 papers, 2012 to 2023). Deficiency of vitamin A due to malnutrition, malabsorption, or dietary lack. "In the mouse model of vitamin A deficiency, supplementation of β-carotene also downregulated the levels of intestinal inflammatory cytokines, TNFα, IL1-β, and IL-6, and immunomodulatory cytokines, IL22, IL23, and IL17." (PMID 37018237, 2023). "Their results indicate that proper vitamin A supplementation was associated with an increase in IL-10 concentration and/or decrease in TNF-α, while vitamin A deficiency was associated with the opposite results." (PMID 28730424, 2018). "In contrast to S. mansoni infection, we found that the numbers of GP61 and GP33 peptide-specific IFNγ- or TNFα-positive CD4+ or CD8+ T cells in the livers, spleens and MLN of LCMV-infected mice were unaffected by vitamin A deficiency." (PMID 22927819, 2012). "Also, the data could suggest that the vitamin A deficiency seen in the positive responders may have resulted in the dendritic cells being altered toward being more inflammatory producing high levels of IL-13 and TNF-α thus creating a favorable environment in which ATRA has an effect." (PMID 29801999, 2018). "Concomitantly, the numbers of IFNγ+ and TNFα+ CD4+ T cells were not decreased in A− mice, indicating a selective defect in the TH2 response induced by vitamin A deficiency." (PMID 22927819, 2012).
wart (4 papers, 2018 to 2024). "This leads to increased production of cytokines such as interferon and tumor necrosis factor, which not only suppress and control the wart but also activate immune cells that recognize and destroy HPV-infected cells." (PMID 39493206, 2024). "Cimetidine activates Th1 cells to produce interleukin (IL)-2, IL-12, tumor necrosis factor (TNF)-α, and interferon (IFN)-γ and their expression correlates with improvement in cellular immunity and wart remission." (PMID 29642499, 2018).
acromegaly (3 papers, 2021 to 2024). Acromegaly is an acquired disorder related to excessive production of growth hormone (GH) and characterized by progressive somatic disfigurement (mainly involving the face and extremities) and systemic manifestations. "A prospective study involving 31 patients with active acromegaly compared to 25 healthy controls showed that TNF-α, IL-6, and activin-A were elevated in patients with active acromegaly compared to controls." (PMID 37584889, 2024).
agammaglobulinemia (3 papers, 2011 to 2024). A decreased level of serum immunoglobulins. "Contrary to what we observed in Congenital Agammaglobulinemia, CVID patients presented with several T-cell imbalances, namely an increase in the production of the pro-inflammatory cytokines IFN-γ and TNF-α, in direct correlation with the up-regulation of activation markers." (PMID 21826211, 2011). "In patients with agammaglobulinemia, there was no S-specific cytokine expression by CD4 T lymphocytes, but consistent IFN-γ and TNF-α expression by CD8+ T cells." (PMID 38132279, 2023).
Aicardi-Goutières syndrome (3 papers, 2020 to 2024). "The type I IFN-regulated gene signature was increased to similar ranges as observed in a historical cohort of patients with Aicardi-Goutières syndrome (AGS), which persisted after start of treatment with TNF inhibitors." (PMID 39264518, 2024).
alexithymia (3 papers, 2019 to 2022). An agnosia that is a deficiency in understanding, processing, or describing emotions. "Similarly, with specific regard to alexithymia, recent studies highlighted a pathogenetic correlation with specific inflammatory markers such as TNF-α and IL-6 exists." (PMID 36140234, 2022). "However, considering that the reduced fatigue was associated with decreased serum TNF-α level and TAS-20 scores, fatigue improvement might be related to reduced inflammation and improved alexithymia in these patients." (PMID 31709006, 2019).
Amebic colitis (3 papers, 2017 to 2019). "TNF-α was measured in colon biopsy samples collected from amebic colitis and control patients by immunohistochemistry." (PMID 28246365, 2017). "We tested the role of IL-25 by administering recombinant IL-25 (rIL-25) to mice during amebic colitis and discovered that IL-25 protected against amebic colitis and that this protection was eosinophil dependent and acted in part by suppressing TNF-α." (PMID 28246365, 2017). "The proinflammatory cytokine TNF-α is known to play a crucial role in intestinal inflammation during amebic colitis." (PMID 28246365, 2017). "We reported here that TNF-α in human colon biopsy specimens was elevated during amebic colitis and that administration of rIL-25 decreased TNF-α in the mouse model during amebic colitis." (PMID 28246365, 2017). "In addition to systemic and local induction of IL-13 and IL-5, a possible role of IL-25 can be hypothesized, as it has recently been shown in protection from amoebic colitis, acting via eosinophils and suppression of TNF-α through a new pathway of innate mucosal immune response." (PMID 31212833, 2019). "Moreover, we demonstrated that eosinophils induced by IL-25 may protect by suppressing TNF-α, as IL-25 suppressed TNF-α levels and neutralization of TNF-α prevented amebic colitis." (PMID 28246365, 2017).
anal carcinoma (3 papers, 2017 to 2024). "Serious side effects were reported by 2 patients treated with a second anti-TNF agent (cerebral vasculitis and anal cancer)." (PMID 36457080, 2022). "It is important to note that the only two anal carcinomas were observed in the TNF-inhibitor group." (PMID 28717771, 2017).
aortic valve calcification (3 papers, 2016 to 2025). "Unexpectedly, our findings showed a negative correlation between TNF-α and the occurrence of aortic valve calcifications (cusps and annulus) and carotid intima media thickness." (PMID 37893519, 2023).
Apathy (3 papers, 2013 to 2022). Apathy is a quantitative reduction of interest, motivation and the initiation and persistence of goal-directed behavior, where often the accompanying emotions, thoughts, and social interactions are also diminished. "The primary aim with this study was to investigate whether blood TNF-α, andits soluble receptors, are associated with apathy symptoms." (PMID 29213854, 2013).
aristolochic acid nephropathy (3 papers, 2015 to 2024). "Etanercept, an inhibitor of TNF-α, significantly attenuated kidney fibrosis and inflammation in a mouse model of aristolochic acid nephropathy." (PMID 38972937, 2024).
asthenia (3 papers, 2016 to 2025). Clinical sign or symptom manifested as debility, or lack or loss of strength and energy. "The treatment of EAMG mice with recombinant human tumor necrosis factor receptor soluble protein (TNFR) Fc blocking endogenous TNF can relieve the symptoms of asthenia, but cannot inhibit the serum anti-AChR antibodies." (PMID 40597804, 2025).
autoimmune gastritis (3 papers, 2018 to 2023). Inflammation of the body fundic mucosa of the stomach. "In vitro culture using biopsy specimens from patients with autoimmune gastritis revealed higher concentrations of tumor necrosis factor-alpha (TNF-α), IL-15, and transforming growth factor-beta 1 (TGF-β1) compared with those from healthy controls." (PMID 37504250, 2023). "In animals with autoimmune gastritis, IL-21 and TNF-alpha are highly expressed." (PMID 30127260, 2018). "Cytokines and inflammatory mediators: Targeting specific cytokines, such as tumor necrosis factor-alpha (TNF-α), interleukin-17 (IL-17), or other key inflammatory mediators, holds promise as a potential therapeutic approach in autoimmune gastritis." (PMID 37706145, 2023).
autoimmune type 1 diabetes (3 papers, 2015 to 2023). Autoimmune disease wherein the body's own immune system attacks and destroys the cells within the pancreas that produce insulin. "Inflammatory cytokines such as TNF-α are thought to play an important role in the pathogenesis of autoimmune type 1 diabetes." (PMID 29310643, 2018).
avascular femoral head necrosis (3 papers, 2008 to 2021). "Relationships of TNF-α gene polymorphisms with interstitial lung fibrosis and femoral head osteonecrosis were carried out in two case-case studies in discharged SARS patients." (PMID 18312678, 2008). "In this study we compared the expression of ADAMTS-7, TNF-α, and Phospho-NF-κB in patients with femoral neck fracture (FNF) and osteonecrosis of femoral head (ONFH) at different stages." (PMID 25653475, 2015).
Azoospermia (3 papers, 2016 to 2024). Absence of any measurable level of sperm,whereby spermatozoa cannot be observed even after centrifugation of the semen pellet. "The frequency of A and G alleles of TNF R1 36 A/G polymorphism was significantly different between cases and controls, and the risk of non-obstructive azoospermia was greater in men with GG genotype (OR=2.298, CI 1.24-4.229)." (PMID 29082371, 2017). "While we did not observe changes in TNF expression in the blood of individuals with CAIS, it does not preclude the involvement of apolipoprotein E (APOE)-relevant mechanisms in azoospermia and other DSD-relevant phenotypes, as it was reported in microglia." (PMID 38212646, 2024).
blepharitis (3 papers, 2022 to 2024). Inflammation of the eyelids near the eyelashes. "Although they are effective in controlling inflammation, TNF-α inhibitors have been associated with various ocular side effects, including blepharitis." (PMID 38337403, 2024). "Different TNF-α inhibitors have been reported to cause blepharitis, like infliximab, a chimeric monoclonal antibody, or adalimumab, a fully human monoclonal antibody." (PMID 38337403, 2024). "The discontinuation of TNF-α inhibitors was associated with the improvement of blepharitis that were refractory to antibiotics and steroids, and it may be necessary." (PMID 38337403, 2024). "Management of TNF-α inhibitor-induced blepharitis is based on the usual conservative and preventive measures outlined in the previous paragraphs." (PMID 38337403, 2024). "Although frequent in general population (8.8%), blepharitis, and chalazions, are known as adverse effects of anti-TNF use." (PMID 35956153, 2022). "However, it is important to highlight reported cases of blepharitis as side effects of systemic therapies, particularly in the context of chemotherapy, bortezomib, cetuximab, TNFα inhibitors, and dupilumab." (PMID 38337403, 2024). "Studies have reported that levels of chronic inflammatory cytokines such as IL-1β, IL-6, TNF-α and IFN-γ are higher in depressed patients, suggesting a similarity in the mechanism of blepharitis development." (PMID 35372440, 2022).
bone metastasis (3 papers, 2022 to 2024). Transfer of a neoplasm from its primary site to bones. "The levels of MIP-1δ, MCP-2, TIMP-1, RANTES, IGFBP3, and TNF-α showed significant differences in the pairwise comparative analysis and may therefore mediate pain associated with bone metastasis." (PMID 35845981, 2022). "In addition, MIP-1δ, MCP-2, TIMP-1, RANTES, IGFBP3, and TNF-α expression levels were significantly different between the preradiotherapy and postradiotherapy groups and may thus be closely associated with bone metastasis-related pain." (PMID 35845981, 2022). "On the other hand, LOH occurs when tumor cells in the bone produce paracrine factors such as tumor necrosis factor (TNF) α and interleukin-1, which in turn hyperactivate osteoclasts and enhance bone resorption in patients with extensive bone metastasis." (PMID 36435947, 2022). "Two adipocyte-derived inflammatory cytokines, interleukin-6 (IL-6) and tumor necrosis factor-alpha (TNF-α), promote the development of bone metastasis." (PMID 38791037, 2024).
brain cancer (3 papers, 2017 to 2022). A primary or metastatic malignant neoplasm affecting the brain. "Radiotherapy of brain cancer is known to induce acute and late pro-inflammatory reactions that involve the production of several cytokines (e.g., TNF-α, IL-1, IL-6, IL-8, IFN-γ), many of which are potent inducers of kinin B1R/B2R expression." (PMID 33003415, 2020). "A highly metastatic lung to brain cancer cell line (SEBTA-001) was perfused at a rate of 2.5 dyn/cm2 with pre-warmed fresh EBM + EGM2 medium supplemented with 2% human serum and 25 pg/mL TNF-α." (PMID 28698503, 2017).
bronchiolitis obliterans (3 papers, 2009 to 2025). "Our study showed that APN suppressed proinflammatory factors (TNF-α and IL-6) through SIRT1- PINK1 signaling-mediated mitophagy, leading to inhibition of lung IR injury, which might mitigate the subsequent occurrence of acute graft rejection and obliterative bronchiolitis." (PMID 34602075, 2021).
burn (3 papers, 2012 to 2024). A traumatic injury involving interruption of tissue cohesiveness that results from exposure to caustic chemicals, extreme heat, extreme cold or excessive radiation. "Increased levels of IL-1α, IL-2, IL-4, IL-10, IFN-γ and TNFα could be detected in culture media of burn injury skin cultures." (PMID 22359539, 2012).
campylobacteriosis (3 papers, 2020 to 2021). Infections with bacteria of the genus campylobacter. "Strikingly, the potent campylobacteriosis ameliorating effects upon carvacrol treatment could also be assessed systemically given that serum concentrations of TNF, IFN-γ, MCP-1 and IL-6 were lower in carvacrol as compared to PLC treated C. jejuni infected mice." (PMID 31921356, 2020). "We mimicked subepithelial cytokine release in the epithelial cell model by adding the major cytokines found in campylobacteriosis, namely of IFN-γ, TNF-α and IL-1β." (PMID 33935732, 2021).
Candidemia (3 papers, 2021). A form of invasive candidiasis where species of CANDIDA are present in the blood. "Our results show that cytokines IL-8, IFN-γ, TNF-α and IL-2 were significantly elevated in the candidemia, compared to the control healthy group." (PMID 34684298, 2021). "Th-1 cytokine IL-8, IFN-γ, TNF-α and IL-2, all of which are important pro-inflammatory cytokines and essential factors in innate immunity, were found in the present study significantly elevated in the patients with candidemia compared to normal healthy control subjects." (PMID 34684298, 2021). "Given the large number of circulating platelets, elevated TNF-α and CXCL8 levels may crucially affect the outcome of candidemia." (PMID 34938671, 2021).
carditis (3 papers, 2011 to 2021). "Additional analysis also indicated TNF-α amounts were higher in Cardiac subjects with more severe pathology compared to those with mild carditis (Mild = 3.1 ± 1.8; Severe = 7.7 ± 2.4; p<0.05)." (PMID 34796122, 2021).
central nervous system demyelinating disorders (3 papers, 2019 to 2023). "Furthermore, previous studies aimed to modulate TNFRs by targeting TNF itself, which might have caused total inhibition of TNF and thus the onset of serious side effects including peripheral and central nervous system demyelinating disorders." (PMID 31877663, 2019). "Although non-selective TNF inhibitors have demonstrated some efficacy in single cases of human SCI and in preclinical SCI models, the risk of adverse effects, including CNS demyelinating disease, exceeds the potential benefit of their use in neurological patients." (PMID 37372129, 2023).
central nervous system tuberculosis (3 papers, 2017 to 2020). A well-circumscribed mass composed of tuberculous granulation tissue that may occur in the cerebral hemispheres, cerebellum, brain stem, or perimeningeal spaces. "Summary of the 17 publications on paradoxical reaction/immune reconstitution inflammatory syndrome of central nervous system tuberculosis treated with TNF-α antagonists." (PMID 33120751, 2020).
cervical adenocarcinoma (3 papers, 2014 to 2020). An adenocarcinoma arising from the cervical epithelium. "For patients with adenocarcinoma of the uterine cervix receiving definitive CRT, prognostic information can be supplemented by MCL1 amplification, the TMN, and the TNF-α H score." (PMID 32527042, 2020).
cervical disease (3 papers, 2008 to 2023). "Our findings may be useful for the identification of genes involved in TNF resistance acquisition and candidate genes which deregulated expression may be associated with cervical disease establishment and/or progression." (PMID 18588690, 2008).
channelopathy (3 papers, 2022 to 2025). Channelopathies are a group of diseases caused by the dysfunction of ion channel subunits or their interacting proteins. "Noteworthy is that Piezo2 channelopathy is also suggested to be linked to the TLR4/IL-6/TNF-α pathway." (PMID 37895134, 2023). "It is noteworthy that the involvement of heat shock protein 70 (Hsp70) activation through the Hsp70/TLR4/Interleukin-6/TNF-α pathway is implicated in DOMS and theorized as the route to Piezo2 channelopathy." (PMID 40863771, 2025). "There is increasing experimental evidence supporting the effects of inflammatory cytokines (mainly tumor necrosis factor-α (TNF-α), interleukin-1β (IL-1β), and interleukin-6 (IL-6)) on cardiac ion channels, and this specific type of channelopathy is termed inflammatory cardiac channelopathy." (PMID 35711306, 2022).
childhood asthma (3 papers, 2007 to 2022). "We found no indication of effect modification by the inflammatory response gene TNF (rs1800629) on the association between traffic-related air pollution and childhood asthma." (PMID 24465030, 2014). "Parental smoking has been consistently related to childhood asthma [U.S. Department of Health and Human Services (DHHS) 2006] and TNF may influence the lung inflammatory response to tobacco smoke." (PMID 17450233, 2007).
cholelithiasis (3 papers, 2016 to 2024). The presence of crystallized deposits forming in the gallbladder or biliary tree, primarily composed of cholesterol, bilirubin, and bile. "In addition, the ELISA results showed that TNF-α, IL-1β, and IL-18 expression was markedly up-regulated in the gallbladder tissues of mice with cholelithiasis compared with the normal control mice." (PMID 37641009, 2023).
chronic otitis media (3 papers, 2007 to 2024). Chronic form of otitis media (disease). "Persistent mucosal hyperplasia of the middle ear mucosa in chronic otitis media resulted from gene and protein expression of inflammatory and apoptotic genes, including NODs, TNFα, Casp3 and cleaved Casp3." (PMID 35433505, 2022).
clonorchiasis (3 papers, 2015 to 2021). Infection of the biliary passages with clonorchis sinensis, also called Opisthorchis sinensis. "TLR4 was involved in immune responses, including increased levels of tumor necrosis factor alpha and interferon gamma during clonorchiasis." (PMID 35127549, 2021). "In our previous study, we showed dramatic changes of TLR2 and TLR4, and production of IFN-γ, IL-6, TNF-α, and IL-10 in the spleen were regulated by TLR4 as demonstrated in a murine model of clonorchiasis using TLR4 defective mice." (PMID 33489026, 2020).
Cn (3 papers, 2013 to 2025). "Similarly, elevated IL-6 and TNF-α levels were reported in a case of cyclic neutropenia associated with RB." (PMID 41250711, 2025). "Considering the implication of TNF-α in a variety of pathological processes and diseases of the CNS, we examined the potential effects of TNF-α on voltage-gated Na+ currents in primary culture of mouse cortical neurons in the current study." (PMID 26112872, 2015). "During a Cn intravenous infection in outbred mice using a serotype D strain (52D), females had significantly higher levels of TNF-α and IFN-γ in the spleen and plasma on day 6 post-infection compared to males, suggesting that the female immune response was more responsive to a Cn infection." (PMID 23741297, 2013).